LAT (linker for activation of T cells)
Diseases named in the same sentence as LAT in open-access papers (continued):
Sharing a sentence is not in itself a finding about the gene and the disease.
tumor (33 papers, 2010 to 2025). "In the immune system, Hsp90 is crucial for regulation of LAT expression in activated T cells, associated with T cell activation and activation of tumor-specific immune responses." (PMID 36674869, 2023). "Linker for activation of T cells (LAT) is the nucleation site of the multiprotein signaling complex, which is essential for the function and differentiation of T cells; thus, its association with tumour prognosis is expected." (PMID 35610596, 2022). "Additional work is also needed to understand the impact of 5’LAT deletions on attenuation and tumor formation." (PMID 39990410, 2025). "In vivo studies will be critical to understand the impact of 5’LAT deletions on attenuation and tumor formation." (PMID 40853964, 2025). "An increased uptake of essential amino acids (EAAs) has been found in tumor tissues when compared to the adjacent normal parts, which is mediated by amino acid transporters including the l-type amino acid transporter (LAT) family." (PMID 34681614, 2021). "A [18F]-FET PET signal results from specific tracer uptake into tumor and endothelial cells depending on tumor cell density and microvascular density mediated by LAT amino acid transporters." (PMID 24759867, 2014). "Cytotoxicity of GEM and 5-FU was significantly enhanced in combination with 10 mM BCH, indicating additive effect of LAT inhibitor on anti-tumor activity of GEM and 5-FU in HuCCT1." (PMID 24131658, 2013). "Inhibiting L-amino acid transporter 2 (LAT2) or treating tumor cells with LAT inhibitors can downregulate the expression of CD47, enhance macrophage infiltration and phagocytosis of tumor cells, and improve cancer treatment by interfering with LAT2-mediated amino acid uptake." (PMID 40534850, 2025). "Tumor bulk RNA-Seq data highlighted that the tumor expression of 5/32 genes (IRF1, IKZF1, SPI1, SH2B3, LAT) was each strongly correlated (Spearman’s ρ > 0.5) with at least one intra-tumor T/myeloid cell infiltration marker (CD4, CD8A, CD11B, CD45) in every one of the cancer types." (PMID 40428397, 2025). "Meanwhile, targeting the PTMs of key signaling molecules involved in TCR activation, such as ZAP70 and LAT, could restore T cell activity, enhance tumor recognition, and improve the anti-tumor immune response." (PMID 40040703, 2025). "Therefore, the augmentation of T-cell activity in vitro does not necessarily translate to increased efficacy in vivo, highlighting the need for further research into the in vivo impact of 2KR LAT on anti-tumor immunity." (PMID 39223632, 2024). "According to our findings and previous literatures, we speculate that LAT, as a protective gene, takes a good effect on preventing tumor metastasis and deterioration in HNSCC." (PMID 33737696, 2021). "More importantly, the expression of LAT is increased in many types of tumor cells." (PMID 24295213, 2013). "The BPA levels in quiescent tumor cells and low-LAT-expressing tumor cells may be also improved by sonoporation." (PMID 24295213, 2013). "They found that the α,α-cycloalkyl amino acids, known as cis- or trans-ACBC, caused tumor cells to accumulate more 10B atoms than L-BPA and its short-chain lipid amino acid derivatives in several cell lines (C6, U81, and A172) expressing the L-type amino acid transporter (LAT)." (PMID 35433432, 2022). "By detecting the phosphorylation level of well‐established TCR downstream kinases including ZAP70, LAT, and ERK, we found that T cells were activated after culturing with medium from tumor cells treated with either DU101 or DU102 or with Arf1 knockdown." (PMID 39225354, 2024). "Compared to normal tissues, significantly higher expression for SKAP1, LAT and lower expression for CD1D, CD79B, CETP, PTGDS was found in tumor tissues in the TCGA-BRCA cohort." (PMID 37598257, 2023).
tumor (continued). "In our study, we found that LAT was highly expressed in HNSCC patients and correlated with tumor metastasis and prognosis, and those patients with higher expression of LAT surprisingly presented lower risk scores and better survival." (PMID 33737696, 2021). "[18F]FET is a non-natural amino acid transported by the amino acid transport system L (LAT), of which particularly the LAT1 isoform is expressed in a variety of tumour cells." (PMID 34223953, 2021). "Lastly, we observed an inverse relationship between the expression of PTPRN2, LAT and SLC39A5 genes and HR of tumour recurrence from the TCGA PRAD dataset." (PMID 31221986, 2019). "The expression of several lymphocyte signaling molecules, including CTLA4, LAT, PDCD1, and ZAP70, was maintained in the transition from human tumor to CX, and was particularly prominent in the CXs derived from D61540." (PMID 24278200, 2013). "Further investigation revealed that the TCR signaling pathway was significantly activated in hCT3 AbTCR T cells after co-culturing with NBEB tumor cells for 2 h compared to mock, CT3 CAR, and CT3 AbTCR T cells, with increased expression of phosphorylated ZAP70, SLP76, and LAT." (PMID 41027430, 2025). "Regardless, immunohistochemical validation of protein expression failed to convincingly support gene expression data and suggests that LAT protein expression is typically absent or low in most tumor tissues." (PMID 34885177, 2021). "LAT and NFE2L3 were upregulated in tumor samples, while HOXD3 was downregulated." (PMID 31777602, 2019). "However, the expression of 2KR LAT does not exhibit a clear impact on tumor clearance." (PMID 39223632, 2024). "A divergent pattern of phosphorylation of Zap70, LAT, Akt and STAT6 was noted in patients with or without an objective tumor response." (PMID 20856802, 2010).
infection (28 papers, 2009 to 2025). The state of being infected such as from the introduction of a foreign agent such as serum, vaccine, antigenic substance or organism. "Consistent with that view, infection of LAT‐deficient DN3 γδint cells with LAT‐expressing retrovirus induced the surface expression of CD5 and of high levels of γδ TCR as observed on a fraction of WT DN3b γδ+ cells." (PMID 35128689, 2022). "We report here that, in contrast to wild type HSV-1, DCs were susceptible to infection by a recombinant HSV-1 expressing murine CD80 (B7-1) under the LAT promoter." (PMID 24475315, 2014). "These constructs were used for production of retroviral particles and infection of LAT-deficient J.CaM2.5 cells." (PMID 22662118, 2012). "As expected, and in contrast to the LAT-minus–γ34.5-plus virus, all mice infected with LAT-minus and γ34.5-minus viruses survived infection with 1 × 102 pfu/eye of the infected virus, suggesting that LAT affects γ34.5 expression and thus neurovirulence." (PMID 40872775, 2025). "At a dose of 1 × 102 pfu/eye, 10 of 10 IFNαβR−/− mice infected with the LAT-plus virus survived infection (100% survival), while 0 of 10 IFNαβR−/− mice infected with the LAT-minus virus survived infection (0% survival) (1 × 102, p < 0.0001, Chi-square)." (PMID 40872775, 2025). "Maintaining the transcription of the LAT gene, maintaining the latent state, inhibiting lysogenic infection, and thus inhibiting the progression of infection, is a good balance for stabilizing the patient." (PMID 34345215, 2021). "Then, we tested the protective efficacy of hu-LAT-27 mAbs against in vivo infection with HTLV-I using our humanized mouse model." (PMID 26848684, 2016). "Infection of TG neurons with an HSV-1 mutant expressing LacZ under control of the LAT promoter showed activation of the LAT promoter and RT-PCR analysis confirmed that both HSV-1 and PRV express LATs during latency in vitro." (PMID 20927329, 2010). "The latency-associated transcript (LAT) of HSV-1 has multiple functions, including enhancing latency reactivation, anti-apoptotic activity, T cell exhaustion, and modulating host immune responses to infection." (PMID 40872775, 2025). "In contrast, naive ILC2 lacking Slc7a5 exhibited comparable CD98 surface expression but were unable to maintain surface CD98 upon activation by infection—again suggesting Slc7a5 is proportionally increased and constitutes an elevated proportion of LAT heterodimers following ILC2 activation." (PMID 36571761, 2023). "Deficiencies in CD4, LCK, LAT and ITK have all been associated with immunodeficiency syndromes and an increased risk of childhood infections, highlighting their importance in determining infection risk." (PMID 35608955, 2022). "This mAb (hu-LAT-27) was reported to block horizontal HTLV-1 infection in animal models, suggesting that hu-LAT-27 may be a candidate passive immunization drug against infection with HTLV-1." (PMID 32012672, 2020). "An important question is whether a similar early expression from the LAT promoter followed by a transition into the lytic cycle would also occur in TG neurons during infection in female mice." (PMID 31396171, 2019). "The ratio of LAT/EP0 was also significantly lower in the high-than in the low-MOI infection." (PMID 21134263, 2010). "In particular, the UL7 tegument protein may be a factor restricting viral proliferation; the Vhs protein is capable of preventing antigen signal transfer to adaptive immunity from the innate immune response during infection; and the LAT gene is related to latency establishment and maintenance." (PMID 29062310, 2017). "Specifically, this group demonstrated that from three days post-infection, the lytic phase expression was shut down whereas the expression from the LAT promoter was highly variable, suggesting that certain neuronal subtypes may be more permissive than others for LAT expression during latency." (PMID 28644417, 2017).
infection (continued). "However, the effect of various LAT mutant viruses in the absence of type-1 IFN during primary infection may not be associated with histone modifications." (PMID 40872775, 2025). "DEGs indicating positive activation of CD8+ cells, such as ZAP70 or LAT, were overexpressed at day 7pi, which suggests that CD8+ T cells are responding to the infection." (PMID 37920474, 2023). "Then, we combined LAT expression data with disease score values, and this allowed us to define a group of mice denominated HSV-2 with evident sign of infection in mice (HSV-2esi)." (PMID 33287823, 2020). "In a previous screen of miRNAs expressed in LAT-KI T cells, we observed overexpression of miR-155 in LAT-KI CD4+ T cells compared to WT CD4+ T cells proliferating in response to infection by H. polygyrus or in response to transfer to an immunodeficient host." (PMID 26121028, 2015). "LAT regulates immune responses to infection, and no other studies have evaluated the inter-relationship of LAT with IFNs and γ34.5 in vivo or in vitro." (PMID 40872775, 2025). "The infection of the tested tonsil fragments was confirmed and shown to be specific (LAT-27 vs. non-specific IgG2)." (PMID 36839454, 2023). "Consistent with the absence of putative CTCF-binding sites, CTCF was not enriched at the LAT promoter (LAP) or at the cellular GAPDH pseudogene relative to the nonspecific antibody control upon infection with either ΔCTRL2 or CTRL2R virus." (PMID 29437926, 2018). "The protective effect was hu-LAT-27-specific since the control anti-CEA did not confer protection against the infection." (PMID 26848684, 2016). "These miRNAs (and the corresponding pre-miRNAs) are expressed as late gene products in Vero cells from unknown promoters (deletion of the LAT promoter does not affect their expression during lytic infection as it does during latency)." (PMID 30755517, 2019). "Thus, the effect of a fairly short delay in phosphorylation of LAT or WAS, for example, could potentially have a major impact on the number of antigen-specific T cells responding to an infection." (PMID 25147952, 2014). "Similar to LAT-plus infected mice, IFNαβR−/− mice infected with LAT1.5kb were protected from death, while infection with the LAT811bp virus was similar to that of LAT-minus, suggesting that increased pathogenicity in the absence of LAT depends on the second half of 1.5 kb LAT." (PMID 40872775, 2025).
cancer (22 papers, 2013 to 2025). A tumor composed of atypical neoplastic, often pleomorphic cells that invade other tissues. "Other significant genes, including RIPOR2, FAM30A, DLX4 and LAT, are associated with inflammatory/immune processes and various cancer etiologies." (PMID 39020437, 2024). "The expression of the heterodimeric glutamine antiporter Slc7A5/Slc3A2 (LAT/CD98) is associated with elevated mTORC1 activity in cancer." (PMID 31817676, 2019). "For rs2070721, rs3740688 and rs4788115, the allele that increased cancer risk also increased expression of IRF1, SPI1 and LAT, respectively, in the eQTLGen data." (PMID 40428397, 2025). "LAT expression has been found to be increased in many cancers, and it is essential for cell growth and protein translation regulation through the mTORC1 pathway." (PMID 41008653, 2025). "Various LAT-1HD targeting approaches for cancer treatment and brain delivery are currently under investigation." (PMID 35408997, 2022). "The compound 2-Amino-2-norbornanecarboxylic acid (BCH) is regarded as a classical LAT inhibitor which reduces cancer cell growth and induces apoptosis." (PMID 29695141, 2018). "The system L amino acid transporter (LAT) has an important role in the transport of various amino acids, and there have been reports about the relation of this system to cancer." (PMID 24168110, 2013). "Recent reports also showed that the inhibition of LAT activity by BCH resulted in the suppression of cell proliferation in various cancers." (PMID 24131658, 2013). "Controlled modulation of LAT activity either through altered phosphorylation of LAT, or by amino acid substitution in the sequence of LAT, has been considered as a potential strategy to enhance the efficacy of adoptive immunotherapy in cancer using chimeric antigen receptor or CAR T-cells." (PMID 40428397, 2025). "The increased metabolic activity of cancer cells is exploited in BNCT, also associated with increased expression of transporters from the SLC (LAT) protein family, which results in a higher concentration of the 10B compound in cancer cells compared to normal cells." (PMID 39937023, 2025). "Conversely, the loss of LAT in exhausted T cells may be important for their lack of responsiveness in cancer immunotherapy." (PMID 40463269, 2025). "However, although 11C-MET accumulated cancers preferentially by large amino acid transporter (LAT), an elevated accumulation was also observed in normal tissue such as liver, pancreas, and pituitary gland tissues, which makes its use difficult in clinical settings." (PMID 34198874, 2021). "In cancer cells, MYC plays a substantial role in promoting the transcription of the L-type amino acid transporter (LAT) (Na+-independent transporters), which transports neutral AAs into cells." (PMID 41008653, 2025). "To determine the cellular function of LAT, we chose 2 different HNSCC cancer cell lines, SCC-4 and UM-SCC-47, for in vitro knockdown experiments." (PMID 39854737, 2025). "Other significant genes, such as LAT, DLX4 and POLD4, are related to inflammatory/immune processes and various cancer types." (PMID 39020437, 2024). "We found that some tertiary lymphoid structure-related genes such as LAT, RBP5, SKAP1, and CCR6 were positively correlated with MHCsig in pan-cancer." (PMID 38714579, 2024). "We demonstrated that ICAM-1 is localized within the cancer-γδ T immune synapse along with other classical immune synapse proteins, including LFA-1 and linker for activation of T cells (LAT)." (PMID 33846331, 2021). "The L-type amino acid transporter (LAT) family is a pivotal uptake route of EAAs and consists of four members (LAT 1–4); LAT1 has been considered especially crucial to cancer biology and has a higher expression in cancer cells than in normal cells." (PMID 33436954, 2021). "According to the KEGG analysis, CHST11 may participate in PD‐L1 expression and PD‐1 checkpoint pathway in cancer by regulating genes TICAM2, LAT, TLR2, CD4, STAT3, NFKBIE and CD3D." (PMID 36062845, 2023).
cancer (continued). "The protein encoded by this gene was phosphorylated by ZAP-70/Syk protein tyrosine kinases following activation of the T-cell antigen receptor (TCR) signal transduction pathway 32, Interestingly, the role of LAT gene in cancers has never been reported." (PMID 31777602, 2019).
head and neck tumors (1 paper, 2021). "We show that LAT expression is significantly upregulated in head and neck tumors compared with noncancer controls, a phenomenon that was recapitulated by our gene expression data." (PMID 34885177, 2021).
hematopoietic cancer (1 paper, 2024). "Furthermore, we found that expression levels of ZAP70, FYN, GRAP2, ITK, and LCK as well as two further TCR pathway kinases, PLCG1 and LAT, were highest in human T-ALL cell lines compared with other hematopoietic cancer lines." (PMID 38618957, 2024).
inflammation (1 paper, 2013). Aberrant reaction of the microcirculation characterized by movement of fluid and leukocytes from the blood into extravascular tissues. "In-vivo allergen-induced airway inflammation study reported that overexpression of LAT prevented the development of airway inflammation with pronouncing reduction of inflammatory cells and IL-4 in BALF." (PMID 23360572, 2013).
LAT also shares sentences with these, for which no sentence is quoted: melanoma (2 papers); allergies (1); Anxiety (1); B cell lymphoma (1); basophilic leukemia (1); breast carcinoma (1); Brody myopathy (1); bronchiectasis (1); common variable immunodeficiency 3 (1); endometrial cancer (1); Fabry disease (1); gestational diabetes (1); GM2 gangliosidosis (1); helminth infection (1); herpesvirus infections (1); HIV-1 infection (1); HTLV infection (1); IgG4-related disease (1); immunodeficiency 52 (1); lichen (1); lysosomal storage disease (1); malaria (1); Medullary Thyroid Carcinoma (1); microcephaly (1); mucopolysaccharidosis (1); neuroblastoma (1); Obesity (1); peritoneal adhesions (1); pneumonia (1); primary immunodeficiency (1).
A further 5 diseases each share a sentence with LAT in 1 paper.